ANGPTL4 (angiopoietin like 4)
Diseases named in the same sentence as ANGPTL4 in open-access papers (continued):
Sharing a sentence is not in itself a finding about the gene and the disease.
lung carcinoma (27 papers, 2009 to 2026). "Furthermore, angiopoietin-like 4 (ANGPTL4) derived from exosomes contributes to angiogenesis, suggesting that it is a potential diagnostic biomarker of lung cancer." (PMID 34193120, 2021). "In conclusion, the increased presence of ANGPTL4 due to HIF-1α accumulation that is caused by nickel in lung cells may be one mechanism by which nickel exposure contributes to lung cancer progression." (PMID 31963541, 2020). "Recent studies have shown that exosomes derived from lung cancer cells under hypoxic conditions exhibit significantly higher levels of the protein angiopoietin-like 4 (ANGPTL4) compared to those under normoxic conditions." (PMID 40328736, 2025). "ANGPTL4 is known to promote gefitinib resistance in lung cancer by regulating the NLRP3/ASC/Caspase 8 pathway." (PMID 38731835, 2024). "Hypoxia not only increases the expression and secretion of ANGPTL4 in lung cancer cells, inhibiting ferroptosis and mediating radiation resistance, but also allows ANGPTL4 protein to be loaded into exosomes derived from hypoxic tumor cells." (PMID 38694500, 2024). "Six genes (PGK1, ENO2, GPI, PEKP, ALDOA, and ANGPTL4) were reported as hypoxia-related genes in lung cancer." (PMID 38248716, 2023). "The remaining DEGs, DDIT4 and ANGPTL4, were recently identified as candidate genes for the prediction of survival outcomes in lung cancer and OvCa patients." (PMID 37444459, 2023). "Our study revealed that ANGPTL4, as a secretory protein, was not only highly up-expressed in hypoxic lung cancer cells, but also enriched in hypoxic exosomes secreted in the extracellular environment." (PMID 36050447, 2022). "Compared with normoxia, hypoxia treatment resulted in robust induction of ANGPTL4 in human lung cancer A549 and H1299 cells." (PMID 36050447, 2022). "Our previous study using tandem mass tag (TMT) quantitative proteomic analysis has demonstrated that ANGPTL4 encapsulated in hypoxic lung cancer cell-derived exosome cargoes was richer than that in normoxic exosomes." (PMID 36050447, 2022). "This study explored the role of ANGPTL4 in aerobic glycolysis, glutamine consumption and fatty acid oxidation in nonsmall cell lung cancer (NSCLC) cells." (PMID 35285130, 2022). "In terms of angiogenesis, radiation-induced ANGPTL4 derived from exosomes contributes to angiogenesis and lung cancer cell migration, suggesting that exosomal ANGPTL4 is a therapeutic target." (PMID 34193120, 2021). "A transwell migration assay was performed to confirm the function of ANGPTL4 and metformin on migration ability in lung cancer cells." (PMID 31963541, 2020). "We screened the expression of ANGPTL4 in various normal cell lines BEAS-2B, MRC-5, and WI-38 and tumour lung cell lines A549, H1355, H1299, H1975 CL1-0, and CL1-5 to investigate the roles of ANGPTL4 in lung cancer progression." (PMID 31963541, 2020). "The results suggested that ANGPTL4 reliably promotes lung cancer cell migration and verified the inhibitory effect of metformin." (PMID 31963541, 2020). "The objective of the present study was to evaluate the role of ANGPTL4 in lung cancer and normal cell lines under NiCl2 exposure and investigate the preventive effect of metformin on NiCl2-activated ANGPTL4 via ROS accumulation." (PMID 31963541, 2020). "In this study, we assessed the role of ANGPTL4 in lung carcinogenesis under nickel exposure and investigated the effects of the antidiabetic drug metformin on ANGPTL4 expression and lung cancer chemoprevention." (PMID 31963541, 2020). "Notably, non‐small cell lung cancer (NSCLC) ranked second in terms of ANGPTL4 expression levels and it is among the well‐known age‐dependent cancers." (PMID 41347893, 2026). "In addition, ANGPTL4 can be secreted into exosomes by lung cancer cells and FMNL2 controls exosome secretion." (PMID 39479958, 2024). "Firstly, the mechanism and signaling pathway through which ANGPTL4 regulates lung cancer cell proliferation and invasion remain unknown." (PMID 38159259, 2023).
lung carcinoma (continued). "Other study found that ANGPTL4 could regulate glutamine metabolism and fatty acid oxidation in lung cancer cells." (PMID 38159259, 2023). "High-risk genes in the model, including ANGPTL4, LDHA, and NPAS2, have been reported to promote angiogenesis, glycolysis, drug tolerance, the invasive and migratory potential, and cell cycle and apoptosis in lung cancer patients or cell lines." (PMID 35295857, 2022). "Therefore, in recent years, research on ANGPTL4 in tumour function has found that activation of ANGPTL4 in lung cancer cells by hypoxia inducible factor‐α (HIF‐α) can promote tumour cell proliferation." (PMID 35285130, 2022). "Tumor cell-derived human angiopoietin-like protein 4 (ANGPTL4) has been shown to disrupt vascular endothelial cell connections, enhance pulmonary capillary permeability, and facilitate tumor cell protrusion through the vascular endothelium, which is involved in lung cancer." (PMID 36245988, 2022). "ANGPTL4 was relevant to NSCLC progression and regulated epithelial-mesenchymal transition via ERK pathway, indicating that ANGPTL4 is vital for the proliferation and metastasis of lung cancer, and may regard as a brand-new target for the treatment of lung cancer." (PMID 35833114, 2022). "Although we have demonstrated that ANGPTL4, as an autocrine factor, contributed to hypoxia-induced radioresistance in lung cancer cells by inhibiting the ferroptosis pathway, the mechanism of ANGPTL4 as a paracrine factor-mediated radioresistance of normoxic lung cancer cells remains unclear." (PMID 36050447, 2022). "We examine TAM roles from pre-metastatic niche formation to tumor colonization, using breast and lung cancer brain metastases to illustrate how TAMs disrupt the BBB and facilitate immune evasion through molecules like ANGPTL4 (angiopoietin-like 4) and MMP9." (PMID 41727473, 2026). "Angiopoietin-like protein 4 (ANGPTL4) is a multifunctional cytokine that is involved in both angiogenesis and metastasis, but its role in lung cancer is still not clear." (PMID 31963541, 2020).
hyperlipidemia (26 papers, 2012 to 2026). "The sialylated form of ANGPTL-4 then binds to glomerular endothelial cells and reduces proteinuria but also inhibits LPS, which causes hyperlipidemia." (PMID 40968277, 2026). "This evidence reveals that induction of ANGPTL4 lead to an increase in ROS levels, which promotes hyperlipidemia-associated CRC metastasis." (PMID 32641980, 2020). "Results in over 30,000 subjects from non-diabetic and population-based studies have confirmed that variants in ANGPTL4 reduce triglyceride and exert protective effects against hyperlipidemia." (PMID 24736372, 2014). "Although ANGPTL4 has been verified to maintain normal cardiovascular functions through its ability to control plasma lipids, its role and molecular mechanisms in regulation of hyperlipidemia-associated CRC metastasis remain incompletely understood." (PMID 32641980, 2020). "ANGPTL4 might play a significant role in the mechanism underlying proteinuria in hyperlipidemia patients." (PMID 32280690, 2020). "No wonder only these two methods could detect the protective effect of the variants in ANGPTL4 against hyperlipidemia, in the Dallas Heart Study data analysis." (PMID 24736372, 2014). "ANGPTL4, plays a critical role in regulating reactive oxygen species (ROS) production, which might provide new targets for improving outcomes in patients with hyperlipidemia-associated CRC metastasis." (PMID 38365849, 2024). "This approach in treatment leads to activation of the systemic and local feedback loop of ANGPTL-4 expression, which then worsens hyperlipidemia of nephrotic syndrome and leads to unsatisfactory responsiveness of proteinuria." (PMID 40968277, 2026). "Our findings in mice with a humanized lipoprotein profile suggest that liver-specific targeting of ANGPTL4 holds therapeutic promise for the treatment of hyperlipidaemia and asCVD." (PMID 39259836, 2024). "In a lipopolysaccharide (LPS)-induced nephropathy model, ANGPTL4 gene knockout alleviated hyperlipidemia and proteinuria." (PMID 39840089, 2024). "Animal studies in mice have demonstrated that ANGPTL4 stimulates hyperlipidemia and hepatic steatosis but reduces blood glucose and ameliorates glucose tolerance." (PMID 38140923, 2023). "Angiopoietin-like protein 4 (Angptl4) is a key gene in the regulation of lipid and glucose metabolism, and hyperlipidemia levels were significantly reduced in Angptl4 knockout mice." (PMID 36147301, 2022). "We also found that ANGPTL4 was positively correlated with TG levels in patients with hyperlipidemia-related kidney injury but negatively correlated with the level of proteinuria in patients." (PMID 33853533, 2021). "Serum ANGPTL4 levels (HL-Pro/HL-NPro group) were positively correlated with total cholesterol (TC) and triglyceride (TG) levels in hyperlipidemia patients." (PMID 32280690, 2020). "We investigated the relationship between ANGPTL4 expression in serum or urine and blood lipid or urine protein levels of patients with hyperlipidemia- (HL-) related proteinuria." (PMID 32280690, 2020). "Although we found that NOX4 and ANGPTL4 expression was associated with CRC progression in a clinical database, the coincidence of CRC metastasis and hyperlipidemia in patients should be further examined." (PMID 32641980, 2020). "Angptl4 null mice (Angptl4−/−) are protected from excess glucocorticoid-induced hepatic steatosis and hyperlipidemia." (PMID 22640645, 2012).
hyperlipidemia (continued). "Variants in ANGPTL3 (SLP = −12.68) and ANGPTL4 (SLP = −4.79) also appear to be protective against hyperlipidaemia, although the result for ANGPTL4 is not exome-wide significant." (PMID 38454133, 2024). "Dysregulation of ANGPTL4 in podocytes under hyperlipidemia may be enacted through the AMPK/ACACA signalling pathway, which plays a crucial role in exercise-induced AMPK/ACACA activation in skeletal muscle." (PMID 38574398, 2024). "ANGPTL4 is highly expressed in the endothelial cells, leading to hyperlipidemia." (PMID 35205232, 2022). "Notably, serum or urine ANGPTL4 levels indicated the degree of proteinuria or hyperlipidemia, respectively, in HL patients." (PMID 32280690, 2020). "Further dissection of whether ANGPTL4 expression is regulated by hyperlipidemia-induced cytokines would be of interest." (PMID 32641980, 2020). "The results for ANGPTL4 are not statistically significant after correction for multiple testing but it can be seen that they are consistent with the possibility that LOF variants lower hyperlipidaemia risk modestly, with OR 0.78 and SLP −1.84." (PMID 38454133, 2024). "By identifying that the induction of ANGPTL4 results in an increased ROS production level, the results of this study suggest a potential mechanism for hyperlipidemia-regulated CRC metastasis and indicate that ANGPTL4 may be a potential target for elimination or prevention of CRC metastasis." (PMID 32641980, 2020). "This study showed that the activation of the ANGPTL4/IL-8/NOX4 axis and KRAS is essential for hyperlipidemia-promoted metastasis." (PMID 37649607, 2023). "As the key inhibitors of LPL, the ANGPTL family members ANGPTL3 and ANGPTL4 interfere with LPL activity in different ways, leading to increased levels of TG, TC, and LDL and the development of hyperlipidemia." (PMID 33853533, 2021). "ANGPTL3, ANGPTL4, and ANGPTL8 are important factors in the regulation of the metabolism of lipids and lipoproteins, providing new hope for the treatment of hyperlipidemia." (PMID 32440963, 2020). "This study aimed to investigate the effects of angiopoietin-like 4 (ANGPTL4) on NADPH oxidase 4 (NOX4) expression and reactive oxygen species (ROS) production, which might provide new targets for improving outcomes in patients with hyperlipidemia-associated CRC metastasis." (PMID 32641980, 2020). "Further investigations are warranted to investigate whether ANGPTL4 and/or NOX4 represent a viable target for clinical treatment, particularly for hyperlipidemia patients with metastatic CRC." (PMID 32641980, 2020). "In HIF-1α heterozygous knockout (HIF-1α+/−) mice subjected to CIH, CIH-induced elevations of plasma TC, and adipose tissue Angptl4 were reversed, while adipose tissue HIF-1α overexpression in transgenic mice resulted in hyperlipidemia and an increase of Angptl4." (PMID 27293515, 2016).
hepatocellular carcinoma (23 papers, 2011 to 2026). A malignant tumor that arises from hepatocytes. "Previous studies have reported that elevated ANGPTL4 serum concentrations were associated with high-grade tumors in women with localized breast cancer, and with hepatic metastatic risk in hepatocellular carcinoma." (PMID 32405335, 2020). "High levels of ANGPTL4 are associated with a poor prognosis in solid tumors, such as prostate cancer, melanoma, hepatocellular carcinoma, bladder cancer, scirrhous gastric cancer, giant cell tumor, oral tongue cancer, and tongue squamous cell carcinoma." (PMID 30049845, 2018). "In situ ANGPTL4 expression in tumor cells of primary tumors is associated with poor prognosis and metastatic relapse in patients with localized breast, gastric, head and neck, colon, and hepatocellular carcinoma." (PMID 32405335, 2020). "In contrast, conditioned medium from ANGPTL4-KO hepatoma cells prevented muscle cells from HCV-3a core induced IR." (PMID 37185283, 2023). "Similar to our results, previous studies revealed higher level of ANGPTL4 in the sera of patients with hepatocellular carcinoma and esophageal squamous cell carcinoma." (PMID 35392474, 2022). "The effect of HCV on ANGPTL-3 and ANGPTL-4 gene expression during long-term infection of hepatoma cells in vitro was also studied." (PMID 34360721, 2021). "Angiopoietin-like protein 4 (ANGPTL4), a newly developed diagnostic and prognostic biomarker, acts as a potential therapy target for renal cell carcinoma, prostate cancer and hepatocellular carcinoma." (PMID 32899312, 2020). "Here, we report that GR regulates ANGPTL4 in a CTCF-mediated chromatin context in the human hepatic carcinoma cell line HepG2." (PMID 28056052, 2017). "Although the major function of ANGPTL4 is to regulate adipogenesis, recent studies have suggested diverse roles in various cancers including colorectal cancer, hepatocellular carcinoma (HCC), breast cancer, and prostate cancer." (PMID 28680385, 2017). "In the present study, we show that GR regulated ANGPTL4 in a CTCF-mediated chromatin context in the human hepatic carcinoma cell line HepG2." (PMID 28056052, 2017). "Importantly, ANGPTL4 also participates in inflammation, angiogenesis, and tumorigenesis, such as prostate cancer and hepatocellular carcinoma." (PMID 35893764, 2022). "In addition, activation of pathways downstream of integrins, including ERK and PI3K, is required for ANGPTL4-promoted hepatocellular carcinoma metastasis." (PMID 32641980, 2020). "However, the expression of ANGPTL-4 was higher in patients with hepatocellular carcinoma as compared with those in the other two groups." (PMID 31741709, 2019). "Circulating ANGPTL3 and ANGPTL4 expression was obviously elevated in patients with hepatocellular carcinoma (HCC) compared with patients with chronic hepatitis and the controls." (PMID 35038961, 2022). "ANGPTL4 may be used to indicate prognosis in hepatocellular carcinoma patients." (PMID 30049845, 2018). "As a secreted protein, elevated levels ANGPTL4 protein have also been detected in the serum of hepatocellular carcinoma (HCC) and tumor-bearing mice." (PMID 23925665, 2013). "Change of ANGPTL4 expression and secretion by HCV-3a core protein was assessed by measuring mRNA expression and protein content in the supernatant of hepatoma cells transduced with either HCV-3a core or GFP, respectively." (PMID 37185283, 2023). "In addition, we showed that ANGPTL4 regulates stemness in GBM through the EGFR/AKT/4E-BP1 cascade, which was supported by another study on hepatocellular carcinoma." (PMID 31717924, 2019). "Moreover, we observed an upregulation of ANGPTL4 expression in two models recapitulating HCV-induced peripheral IR, i.e. mice expressing core protein of HCV genotype 3a (HCV-3a core) in hepatocytes and hepatoma cells transduced with HCV-3a core." (PMID 37185283, 2023).